TYK2 (tyrosine kinase 2)
Diseases named in the same sentence as TYK2 in open-access papers (continued):
Sharing a sentence is not in itself a finding about the gene and the disease.
autoimmune disease (continued). "Partial loss of TYK2 function is associated with reduced risk for several autoimmune disorders such as RA and psoriatic disease, conditions treated with immunosuppressive therapy." (PMID 35482673, 2022). "Loss-of-function SNPs of TYK2 (e.g., rs34536443, rs2304256) have been reported to be protective against several autoimmune diseases including T1D9,32." (PMID 36289205, 2022). "For example, TYK2-deficient or chemically-inhibited rodents were revealed to be resistant to experimental autoimmune disease models such as MS and Rheumatoid arthritis (RA)." (PMID 35693820, 2022). "For example, a nonsynonymous, deactivating single nucleotide polymorphism (SNP) in the coding sequence of tyrosine kinase 2 (TYK2) is associated with protection from many autoimmune diseases." (PMID 34508276, 2022). "A meta-analysis of immunochip data in autoimmune diseases identified the TYK2 SNP rs74956615 as associated with RA, T1D, and systemic sclerosis (SSc)." (PMID 34439323, 2021). "Small genetic studies that focused on the TYK2 locus itself were the first to link variants to autoimmune disease." (PMID 34290741, 2021). "This complexity is highlighted by diverse functional and immunological effects of natural mutations throughout the TYK2 gene, with selected SNPs having opposing risk vs protective effects in different autoimmune diseases." (PMID 34290741, 2021). "Small molecule TYK2 inhibitors are under clinical trials for their safety and efficacy in psoriasis, and other autoimmune diseases associated with inflammation." (PMID 33467029, 2021). "Single nucleotide polymorphisms (SNPs) in the GTFSI, NFKB1, and TYK2 genes have been reported to be associated with SSc in other populations and in individuals with various autoimmune diseases." (PMID 34248934, 2021). "Genetic association studies have also linked the TYK2 gene to the risk of developing many autoimmune diseases." (PMID 34439323, 2021). "Previous studies have found that TYK2 polymorphisms are associated with a variety of autoimmune diseases such as RA, SLE, T1D, and multiple sclerosis." (PMID 34248934, 2021). "Tyrosine kinase 2 (TYK2) locus single-nucleotide polymorphisms (SNPs) associated with ankylosing spondylitis (AS) or related autoimmune diseases." (PMID 34290741, 2021). "Surprisingly, even though this variant protects against more than 10 different autoimmune diseases, complete knock-out of TYK2 causes severe susceptibility to infections." (PMID 32477401, 2020). "Humans naturally deficient in TYK2 have increased sensitivity to mycobacterial and viral infections, while TYK2-deficient mice are protected from Th17-mediated autoimmune disease." (PMID 32149730, 2020). "The identification has been replicated in a number of recent analyses, and TYK2 is now recognized as a susceptibility gene in a variety of inflammatory and autoimmune diseases, including type I diabetes (T1D), psoriasis and multiple sclerosis." (PMID 31961910, 2020). "It has been reported that TYK2 LoF exonic SNPs are the primary variants associated with autoimmune disease in the TYK2 locus." (PMID 32149730, 2020). "After many years of genetic association studies, TYK2 is recognized as a susceptibility gene for some inflammatory and autoimmune diseases (AID)." (PMID 31961910, 2020). "The importance of TYK2 gene polymorphisms in autoimmune diseases was supported by a vast majority of the studies." (PMID 31057722, 2019). "Genome wide association studies (GWAS) have identified a single nucleotide polymorphism (SNP; rs34536443) in the TYK2 gene associated with several autoimmune diseases." (PMID 30740104, 2019). "TYK2 protein-coding variants have been associated with several autoimmune diseases, including systemic lupus erythematosus (SLE) and inflammatory bowel disease (IBD)." (PMID 25849893, 2015).
autoimmune disease (continued). "We then used Exomechip data to investigate the association of TYK2 missense variants with two additional autoimmune diseases, SLE and IBD, both of which have been reported previously to harbour associations to genetic variants in this locus." (PMID 25849893, 2015). "While implicated variants were largely trait-specific, 40% of target genes of these variants (2,207 of 5,488) were implicated across more than one autoimmune disorder, with 11 genes implicated across a maximum of 9 traits (e.g., TYK2, ICAM1, ICAM3, TNFIP3, CLEC16A, BACH2)." (PMID 41361473, 2025). "TYK2:p.Pro1104Ala variant confers protection from several autoimmune disorders but predisposes to infection and we show that the mechanism of its action includes an increase of the levels of lymphocytes in all compartments (CD4+, CD8+ and B), but these cells are mainly naive." (PMID 39835539, 2025). "Tyrosine kinase 2 (TYK2) was identified as a Ps risk gene in 2010, with its genetic variation associated with several other autoimmune diseases, including multiple sclerosis, systemic sclerosis, Type 1 diabetes, Crohn’s disease, ulcerative colitis, and systemic lupus erythematosus." (PMID 39684939, 2024). "Moreover, the loss-of-function of TYK2 with SNPs rs34536443 has been known for the protective function against several autoimmune diseases, including T1DM, by diminishing IFN-1, IL12, and IL23 signalling." (PMID 38926794, 2024). "Dysregulated TYK2 expression has been linked to autoimmune diseases." (PMID 38332917, 2023). "Therefore, dysregulation of the expression of TYK2 has been linked to autoimmune diseases, particularly SLE." (PMID 37813633, 2023). "A phenome-wide study on 19 candidate disease targets also indicated that TYK2 loss-of-function mutation might be associated with several autoimmune diseases, supporting therapeutic benefit of pharmacological inhibition." (PMID 36842216, 2023). "Intriguingly, some of the non-synonymous single-nucleotide polymorphisms (SNPs) of TYK2 (rs34536443 and rs2304256) that induce a partial inhibition of TYK2 expression are associated with protection against several autoimmune diseases, including T1D and rheumatoid arthritis." (PMID 36289205, 2022). "Additionalstudies with larger sample sizes are necessary to clarify the impact of eachTYK2 SNP on susceptibility for different autoimmune diseases.Functional studies are also needed to elucidate which are the TYK2SNPs with the highest impact on TYK2 function and, consequently, onautoimmune diseases." (PMID 33949620, 2021). "Given the establishment of TYK2 as a susceptibility gene in auto-inflammation, immunodeficiency and other immune responses as well as in cancer, the prospect of therapies targeting TYK2 in immunodeficiency and autoimmune diseases exists." (PMID 34439323, 2021). "Thus,taken together, these studies suggest the rs2304256 SNP decreases TYK2 activity and,consequently, the inflammatory response and apoptosis, explaining its associationwith protection against autoimmune diseases." (PMID 33949620, 2021). "Autoimmune disease-associated TYK2 variants in European population." (PMID 31961910, 2020). "In addition, in some autoimmune disease processes, TYK2 abnormal expression is associated with diseases, especially lupus erythematosus." (PMID 30974919, 2019). "Interestingly, genetic variants of Tyk2 have been reported to protect against RA, systemic lupus erythematosus, and possibly other autoimmune diseases, such as inflammatory bowel disease." (PMID 28399940, 2017). "Genetic variation in the 19p32/TYK2-ICAM locus has also been associated with several other autoimmune diseases, including psoriasis, multiple sclerosis (MS), Type 1 diabetes (T1D), Crohn’s disease (CD), ulcerative colitis, and systemic lupus erythematosus (SLE)." (PMID 25849893, 2015). "However, TYK2 signaling is associated with the pathogenesis of autoimmune diseases." (PMID 38351043, 2024).
autoimmune disease (continued). "Moreover, the TYK2 gene has been identified as a candidate gene linked to autoimmune diseases." (PMID 37813633, 2023). "Therefore, different SNPs in the TYK2 gene seemto be associated with autoimmune diseases, although the results on individual SNPsare still inconclusive especiallydue to the increase in the number of studies in this field in the last few years indifferent ethnicities." (PMID 33949620, 2021). "Tyrosine kinase 2 (TYK2) is a genetically defined target for autoimmune disease, with first-generation inhibitors showing clinical success in some but not all associated indications." (PMID 42268925, 2026). "TYK2, part of the JAK and antiviral pathways, is recognized as a locus associated with DM and several other autoimmune diseases, including CeD, suggesting a genetic overlap between these diseases." (PMID 39665304, 2025). "TYK2, encoding a member of the Janus kinase (JAK) family involved in IL23 signaling, has been recognized as an important genetic locus in various autoimmune diseases, including sarcoidosis." (PMID 40075078, 2025). "These first-generation inhibitors simultaneously bind to JAK1, JAK2, JAK3, TYK2, and other homologous targets, thereby blocking multiple downstream signaling pathways, thereby treating a variety of autoimmune diseases." (PMID 40746612, 2025). "Building on this, we explored how LigUnity can be integrated with active learning to optimize ligands for tyrosine kinase 2 (TYK2), a therapeutic target for autoimmune diseases." (PMID 41142909, 2025). "Promising results have been found in clinical trials targeting TYK2 in autoimmune diseases, supporting the potential of drug repurposing in type 1 diabetes." (PMID 39271518, 2024). "Currently, research indicates that multiple selective inhibitors of TYK2 have been approved for treating autoimmune diseases, such as plaque psoriasis." (PMID 39726748, 2024). "TYK2 is a candidate susceptibility gene for type 1 diabetes (T1D) and a beneficial effect has been reported for TYK2 inhibitors for other autoimmune diseases." (PMID 38351043, 2024). "Brepocitinib (PF-06700841), also an aminopyrazole derivative, is a JAK1/Tyk2 inhibitor designed as treatment for severe autoimmune diseases." (PMID 37513232, 2023). "It is a selective inhibitor of Tyk2, and, currently, there are clinical trials for it as treatment for various autoimmune disorders." (PMID 37513232, 2023). "Direct inhibition of TYK-2 is currently being discussed primarily in the therapy of dermatological autoimmune diseases where its efficacy and safety are being tested in clinical trials." (PMID 36766795, 2023). "In this study, we developed a highly selective and potent small molecule inhibitor of TYK2 (QL-1200186) to treat autoimmune diseases." (PMID 37845748, 2023). "Taken together, the research and genetic evidence supports the merit of blocking TYK2 as a promising therapeutic strategy against autoimmune-disorders with optimal balance between efficacy and safety." (PMID 35693820, 2022). "A selective TYK2 inhibitor offers a great opportunity to treat autoimmune diseases delivering a potentially differentiated clinical profile compared to currently approved JAK inhibitors." (PMID 35693820, 2022). "The profound potency and high selectivity of TYK2 JH2 small molecule ligands support endeavors to develop clinically effective TYK2 inhibitors with a potentially well-tolerated safety profile for autoimmune disease therapeutics." (PMID 35693820, 2022). "To further investigate the possible effects of the TYK2 SNPs onsusceptibility for autoimmune diseases, we performed meta-analyses of 34 publishedarticles on the field." (PMID 33949620, 2021). "TYK2 abnormalities have been established in several autoimmune diseases such as systemic lupus, rheumatoid arthritis, and multiple sclerosis." (PMID 33467029, 2021).
autoimmune disease (continued). "The pharmacological inhibition of TYK2 (TYK2inibs) is a recognized approach to the treatment of chronic inflammatory and autoimmune diseases and is under consideration for cancer treatment." (PMID 31936322, 2020). "Early genetic association studies have assigned to the TYK2 locus an impact on susceptibility to systemic lupus erythematosus (SLE) and other autoimmune diseases (AID)." (PMID 31961910, 2020). "The JAK kinase family, consisting of the protein kinases JAK 1–3 and TYK2, are attractive targets for pharmacological intervention to treat inflammatory and autoimmune diseases, especially rheumatoid arthritis, as well as several myeloproliferative disorders." (PMID 31578349, 2019). "Single-nucleotide polymorphisms in several transcription factors involved the type I IFN pathway (for example, IRF5, Tyk2, and STAT4) have recently been associated with a number of autoimmune diseases, including SLE and RA." (PMID 20096109, 2010). "Current research suggests that TYK2 is associated with various autoimmune diseases; however, no study has examined the relationship between TYK2 polymorphisms and AAV." (PMID 39726748, 2024). "In addition, Tyk2−/− mice exhibit reduced inflammatory responses in several autoimmune disease models and are resistant to LPS-induced septic shock." (PMID 38683377, 2024). "As a result, TYK2 may be a promising target for drug-dependent inhibition in various common autoimmune disorders, including T1DM." (PMID 38926794, 2024). "Therefore, targeted intervention of TYK2 via small molecule inhibitors has been shown to be a viable option for the treatment of autoimmune diseases." (PMID 37845748, 2023). "However, relatively few clinical trials on these outcomes hinder the assessment of the effectiveness of TYK2 inhibitor treatment on autoimmune diseases beyond plaque psoriasis." (PMID 36842216, 2023). "A greater understanding of TYK2's molecular and cellular characteristics and studies indicating that TYK2 gene polymorphisms are protective against developing SLE will lead to the discovery of therapeutic approaches for autoimmune diseases such as SLE." (PMID 37813633, 2023). "In the past decade, TYK2 became an emerging drug target to treat various human autoimmune diseases." (PMID 35693820, 2022). "Meanwhile, targeting the JH2 domain represents an appealing strategy for the development of clinically well-tolerated TYK2 inhibitors that would have superior efficacy and a favorable safety profile compared to the existing Janus kinase inhibitors against autoimmune diseases." (PMID 35693820, 2022). "Notably, a germline loss-of-function TYK2 mutation (rs34536443; TYK2P1104A) has been reported and hereby confirmed in the Finnish population to be protective against several autoimmune diseases including T1D9,32." (PMID 36289205, 2022). "In addition, pharmacological inhibition of TYK2 is currently used clinically for autoimmune diseases, and now provides promising treatment modalities as effective therapeutic agents against multiple types of cancer." (PMID 34439323, 2021). "JAK1 and TYK2 have been targeted against autoimmune diseases." (PMID 30564118, 2018). "Thus, large genetic studies have identified low frequency variants with relevant functional significance associated with autoimmune diseases (e.g. TREX1 in SLE25 and TYK2 in several autoimmune diseases)." (PMID 29844438, 2018). "Second, the protective effect of the three TYK2 variants in SLE observed in our study highlights that a drug that mimics the effect of the RA-protecting TYK2 alleles may also be effective at treating SLE, and potentially other autoimmune diseases such as IBD." (PMID 25849893, 2015). "However, unlike the “too strong” immune response in autoimmune disease, inherited TYK2 deficiency impairs IL-12/-23-dependent IFN-γ immunity and is associated with an elevated risk of Mycobacterium tuberculosis infection." (PMID 40075078, 2025).
autoimmune disease (continued). "Consequently, the possible therapeutic use of TYK2 inhibitors in autoimmune diseases should take into account their impact on TLR7 expression, which may lead to a low antiviral response in these patients." (PMID 38683377, 2024). "Considering the genetic overlap of autoimmune diseases and the association of these genes with SSc in other populations, we hypothesized that some of the related tag SNPs of GTF2I, NFKB1, and TYK2 may also contribute to susceptibility to SSc in the Chinese Han population." (PMID 34248934, 2021). "Thus, a compound able to modulate the kinase activity of TYK2 could be a successful drug candidate for autoimmune disorders." (PMID 32477401, 2020). "Using TYK2 as a treatment target in autoimmune diseases may have side effects." (PMID 30974919, 2019). "This region is important for the interaction of TYK2 with IFNAR1, its function, as well as for maintaining the expression of IFNAR1 on the cell surface, suggesting that this SNP may reduce the function of TYK2 and thus susceptibility to autoimmune diseases." (PMID 23227085, 2012). "Treatment with the TYK2 inhibitor deucravacitinib, which is approved by the FDA for treating plaque psoriasis and is under clinical investigation for other autoimmune diseases, promoted CRLM." (PMID 40991399, 2026). "The first allosteric TYK2 inhibitor, deucravacitinib, has been approved by the FDA for the treatment of plaque psoriasis and is being used in clinical trials for other autoimmune diseases including inflammatory bowel disease (IBD)." (PMID 40991399, 2026). "Tyrosine kinase 2 (TYK2), a member of the JAK family, has attracted attention as a potential therapeutic target for autoimmune diseases." (PMID 38351043, 2024). "Enrichment analysis revealed that 50 % of the shared genes (STAT4, TYK2, IL2RA, PTPN2, and STAT3) among autoimmune diseases belong to the JAK-STAT pathway." (PMID 39421031, 2024). "Thus, TYK2 inhibitors may have the potential in the treatment for autoimmune diseases." (PMID 36842216, 2023). "A breakthrough TYK2 allosteric inhibitor, Deucravacitinib (BMS986165), is in late-stage clinical development for multiple autoimmune diseases." (PMID 35693820, 2022). "On the other hand, compounds targeting TYK2 JH2 have been shown to efficiently inhibit TYK2-mediated signaling and are in phase 3 clinical trials against autoimmune diseases)." (PMID 33672930, 2021). "Together, our results demonstrate the role of TYK2 in the pathogenesis of RA, SLE and IBD, and provide supporting evidence for TYK2 as a promising drug target for the treatment of autoimmune diseases." (PMID 25849893, 2015). "In the context of autoimmune disease, the role of TYK2 in CD4+ T cells, but not CD8+ T cells, has been well described." (PMID 38351043, 2024). "TYK2-K930R failed to rescue, while TYK2-A928V and TYK2-P1104A, protective in many autoimmune diseases, partially rescued signaling to IFN." (PMID 31961910, 2020). "Furthermore, it can be postulated that different SNPs in TYK2 and IL2RA may play different roles in various types of autoimmune diseases." (PMID 38332917, 2023). "In summary, TYK2 rs2304256 is not neutral but has a potential impact on autoimmune diseases." (PMID 34248934, 2021). "Given that TYK2 belongs to the Janus kinase (JAK) family that exerts effects on a wide range of inflammatory disorders, TYK2 inhibitors may have the potential in the treatment for other autoimmune diseases, such as inflammatory bowel disease, rheumatoid arthritis, and type 1 diabetes." (PMID 36842216, 2023).